CXCR5 (C-X-C motif chemokine receptor 5)
Diseases named in the same sentence as CXCR5 in open-access papers (continued):
Sharing a sentence is not in itself a finding about the gene and the disease.
influenza (continued). "Peripheral TFH subsets in whole blood or fresh human PBMCs of healthy participants have been identified by ex vivo staining following vaccination against influenza, describing memory CD4+CXCR5+ TH cells as the most abundant population." (PMID 27336786, 2016). "Thus far, post‐vaccination changes in numbers of circulating follicular (CXCR5+) CD4+ T cells and plasmablasts (CD19 + CD27 + CD38+) at day 7 were described as some of the best correlates of antibody responses to influenza vaccination." (PMID 38146131, 2024). "cTfh cells share phenotypic and functional properties to GC Tfh cells, and it has been shown that inactivated influenza vaccination (IIV) induces expansion and PD-1/ICOS-activation of CD4+CXCR5+CXCR3+ cTfh type-1 (cTfh1) cells, which correlated with antibody and CD19+CD27++CD38++ ASC responses." (PMID 33976217, 2021). "The expression levels of the main surface markers characterizing peripheral Tfh and Th1 cells (i.e. CXCR5, PD-1 and CXCR3) are shown on HCV-specific CD4 T cells in comparison to influenza- (Flu-) specific CD4 T cells ex vivo in a representative HCV-infected, DAA-cured or healthy donor, respectively." (PMID 34659236, 2021). "When there was influenza infection, Tfr cells was approximately 5–8% of CD4+CXCR5+ cells." (PMID 31382877, 2019). "The administration of trivalent split-virus influenza vaccines was shown to induce the temporary accumulation of circulating ICOS+ CXCR3+ CXCR5+ CD4+ T cells, and up to 60% of these cells were specific for influenza antigens and correlated with an increase in preexisting antibody titers." (PMID 31300682, 2019). "A study of human Tfh shows that CXCR5+ circulating memory-like Tfh cells reactive with influenza protein preferentially recognize peptide epitopes from hemagglutinin, while CXCR5− non-Tfh preferentially recognize nucleoprotein." (PMID 30123218, 2018). "The IFNγ−IL-2+TNFα+ influenza-specific cells in the present study did not express CXCR5, and so do not fit a Tfh definition or the more stringent Tcm definition used in one study." (PMID 23526940, 2013). "Previously identified biomarkers and gene signatures could only predict humoral antibody responses to influenza vaccine in young adults, but not in the elderly, due to the expression of CXCR5 and programmed death-1 (PD-1) genes in circulating Tfh cells." (PMID 33343577, 2020). "In general, CXCR5, compared to CXCR3 and CCR6, is the chemokine receptor that was most prominently expressed on tetramer-positive cells with mean levels of up to 40% for citrulline-specific and 54% for influenza-specific populations while for the general CD4+ population it was only around 10%." (PMID 32423478, 2020). "In addition, our data show that both adjuvanted rGP immunization and LCMV infection significantly enhanced the memory antigen-specific Th1 cell pool after influenza infection, despite differences in the CXCR5– non-Tfh cell populations prior to influenza infection." (PMID 39283916, 2024). "Abundance of PD-1+ CXCR5+ cells has been shown to correlate with influenza vaccine responsiveness in the young but not in the elderly, which could account for why baseline PD-1 expression did not distinguish sero-responders, or between CKD and HC, in our mostly elderly cohort." (PMID 30303980, 2018). "We found that IL-21hi cells exhibited the highest expression levels of Il21, Bcl6, and Cxcr5 but not Foxp3, compared with other cell populations, suggesting that TRH cells but not regulatory T cells express IL-21 in the lung after influenza infection." (PMID 38345472, 2024). "Of note, among influenza- and citrulline-specific cells as well as in the general CD4 population around half of the CXCR3+ cells also expressed CXCR5 and to a lesser extent CCR6 (data not shown)." (PMID 32423478, 2020). "In contrast to this we found only a few influenza-specific cells co-expressing several chemokine receptors, these were mostly CXCR3+ cells carrying CCR6 and/or CXCR5 (data not shown)." (PMID 32423478, 2020).
breast cancer (43 papers, 2008 to 2025). A primary or metastatic malignant neoplasm involving the breast. "The high expression of CXCL13 and CXCR5 in breast cancer tissue was found to be associated with lymph node metastasis, distant metastasis, and a more advanced disease stage." (PMID 39001456, 2024). "High expression of CXCL13 and CXCR5 in breast cancer tissues was found to be associated with increasing stage, lymph node metastasis, distant metastasis, and disease stage, but not with HER2 status, histological type, or tumor size." (PMID 39001456, 2024). "CXCR5 is a protein that has been linked to many human cancers, especially breast cancers with lymph node metastasis." (PMID 37159817, 2023). "CXCR5, another predicted target gene of miRNA-4497, was implicated in the regulation of cell proliferation, invasion and migration in breast cancer, hepatocellular carcinoma, myeloma and other malignancies." (PMID 33579314, 2021). "Similarly, CXCR5+FoxP3+ follicular regulatory T cells have been positively associated with LDH levels in breast cancer (BC)." (PMID 40091778, 2025). "However, a large number of studies have demonstrated that the CXCL13/CXCR5 axis is closely associated with breast cancer growth and lymph node metastasis." (PMID 34947813, 2021). "Gene expression analysis from in vitro mammosphere formation revealed IFNG, CXCR5, CD40LG, TBX21, and IL2RG to be associated with the CSC phenotype and also displayed prognostic value for patients with breast cancer." (PMID 39001456, 2024). "Gene expression analysis revealed IFNG, CXCR5, CD40LG, TBX21 and IL2RG to be associated with the CSC phenotype and also displayed prognostic value for patients with breast cancer." (PMID 38831317, 2024). "A population of cytotoxic T cells was noted with high PD‐1 and CXCR5 expression in the lymph nodes of the breast cancer patients." (PMID 38069525, 2023). "Here, a subpopulation of CXCR5+PD‐1+ cytotoxic T cells was identified with high TIM‐3, ICOS, and CD45RO expression in the lymph nodes from breast cancer patients but showed limited association with the clinical features of the patients." (PMID 38069525, 2023). "Abnormally active CXCL13/CXCR5 signaling enhances cancer cell growth through complex and different mechanisms in breast cancer, intestinal cancer, lung cancer, prostate cancer, oral squamous cell carcinoma, renal cell carcinoma, neuroblastoma, and lymphoma." (PMID 35053457, 2022). "It seems that there is a strong correlation between the CXCL13/CXCR5 axis and breast cancer progression, which have been verified in several studies." (PMID 35702353, 2022). "CXCL13 was secreted by PD-1hiCD8+ T cells in lung cancer, by CD103+CD8+ cells in ovarian cancer, and by CXCR5–PD-1hiCD4+ follicular helper like T cells in breast cancer and nasopharyngeal cancer." (PMID 35552285, 2022). "The characteristics of CD4+CXCL13+ T cells in LR-CHL are very similar to a CXCL13-producing TFH population that lacks CXCR5 expression identified in breast cancer." (PMID 34615710, 2021). "The CXCL13/CXCR5 axis is related to improved outcomes of human epidermal growth factor receptor 2 (HER2)-positive breast cancer." (PMID 34947813, 2021). "The abundance of lymphoid chemokines such as CXCR5 and CXCL13 has been linked to both the presence of TLS and HEV in breast cancer stroma." (PMID 32605588, 2020). "In an early study using CXCR5-expressing breast cancer cells, CXCL13 induced changes in the expression of markers consistent with epithelial-to-mesenchymal transition (EMT)." (PMID 31354634, 2019). "Breast cancer exhibits one of the strongest relationships between CXCL13:CXCR5 axis and tumor progression." (PMID 31354634, 2019).
breast cancer (continued). "The impact of CXCL13/CXCR5 on various types of cancers including breast cancer has recently attracted much interest." (PMID 25990390, 2015). "Our data are in line with recent observation that co-expression of CXCL13 and CXCR5 in breast cancer patients closely correlates with tumor progression and lymph node metastasis." (PMID 25786345, 2015). "Further studies, however, are underway in our laboratory examining the exact consequences of CXCL13/CXCR5 interactions for the development and/or progression of breast cancer in vivo." (PMID 18781150, 2008). "Finally, the expression of novel markers, including CXCR5, has been recently investigated in cancer stem-like cells (CSCs) in 125 patients with breast cancer." (PMID 39001456, 2024). "Studies on the correlation between CXCL13 /CXCR5 signaling axis and gastric cancer, breast cancer, lung cancer and other tumors have been reported, but the correlation of CXCL13 /CXCR5 signaling axis in uterine adhesions remains unclear." (PMID 39456064, 2024). "Of note, a cytotoxic T cell subpopulation expressing high levels of PD-1 and CXCR5 was recently described in the lymph nodes of breast cancer patients with unknown significance." (PMID 39001456, 2024). "Collectively, in the circulation and especially in the regional lymph nodes of breast cancer patients, a subpopulation of CXCR5+PD‐1+ cytotoxic T cells was frequently identified with TCM phenotype, expression of TIM‐3 and ICOS receptors, and had reduced capacity to secrete IFN‐γ." (PMID 38069525, 2023). "Several previous studies have also revealed that CXCL13 suppresses lymphocyte apoptosis in the spleen of pigs after porcine circovirus type 2 infection, while CXCL13 inhibition induces the apoptosis of breast cancer cells through blocking the CXCR5/ERK pathway." (PMID 36613500, 2022). "One study showed that the CXCL13/CXCR5 axis was a good prognostic marker for breast cancer." (PMID 34947813, 2021). "CXCR5, miR-200c-3p, miR-20b-5p, miR-7-1-3p, miR-342-3p, and HPN-AS1 were upregulated genes, while these high expression genes were significantly associated with breast cancer patients’ better overall survival." (PMID 34220926, 2021). "In addition, CXCL13 is involved in the progression of breast cancer cells through the CXCR5/ERK pathway." (PMID 34947813, 2021). "Furthermore, human breast cancer cells MDA-MB-231 express high level of chemokine (C-X-C motif) ligand 13 (CXCL13) which enable the migration of C-X-C chemokine receptor type 5 (CXCR5)–expressing B cells to the tumor." (PMID 31086070, 2019). "Indeed, using real-time RT-PCR and Western blotting analyses we detected CXCR5 mRNA and protein in breast cancer cell line MCF-7." (PMID 25786345, 2015). "Here we show that functional chemokine receptor CXCR5 is expressed in MCF-7 breast cancer cells." (PMID 25786345, 2015). "Breast cancer cells might interact through CXCR5/CXCL13 interactions to organise cellular cluster formation and compartmentalisation as has been shown for B cells in renal allografts and in salivary glands of patients with Sjogren's syndrome." (PMID 18781150, 2008). "However, we observed a strong (P=0.0004) correlation between the expressions of CXCL13 and CXCR5 in breast cancer tissues, indicating a biologically relevant role of CXCR5 in vivo." (PMID 18781150, 2008). "This way, CXCL13 and its ligand might contribute significantly to tumour formation, and therapeutic interventions aiming at interrupting CXCL13/CXCR5 interactions might be of benefit for the clinical course of patients with breast cancer." (PMID 18781150, 2008).
breast cancer (continued). "However, we detected a strong and significant (P=0.0004) correlation between copy numbers of both genes analysed within breast cancer tissue, indicating a biologically relevant role of CXCR5 as a receptor for CXCL13 in this solid tumour." (PMID 18781150, 2008). "In our view, the most perspicuous explanation for the increased presence of CXCL13 in breast cancer is that CXCR5/CXCL13 interactions might function in a similar way as they do in lymphatic tissue." (PMID 18781150, 2008). "Thus, CXCL12 and CXCL13/CXCR5 expression in the LNs of these breast cancer patients may be more relevant than other chemokines or receptors studied for LN involvement, resulting in a worse prognosis." (PMID 40584290, 2025). "However, another study suggested that CXCL13 may inhibit tumor growth in breast cancer through CXCR5/ERK signaling." (PMID 38075694, 2023). "In addition, expression levels of CXCL13 and CXCR5 could be potential biomarkers for diagnosis and prognosis for breast cancer." (PMID 35702353, 2022). "Additionally, a very recent study investigated the role of NRF2 in the transcriptional regulation of the chemokine CXCL13 and its receptor CXCR5, two known drivers of breast cancer cells migration and metastatic dissemination, from primary breast tumors to lymph nodes." (PMID 33805996, 2021). "Thus, CXCR5 expression may be closely connected to migration potential of breast cancer cells, similar to the well documented example of CXCR438." (PMID 25786345, 2015). "Therefore, we favour the third possible explanation, suggesting that breast cancers cells might supply themselves with a growth advantage by the expression of CXCR5 and the release of CXCL13 in vivo." (PMID 18781150, 2008). "Of 321 formalin-fixed paraffin-embedded primary tumor tissue samples of patients with early breast cancer treated with chemotherapy, mRNA expressions of CXCL12, CXCL13, and CXCR5 were studied." (PMID 39001456, 2024). "There are few articles about the role of new chemokine receptors, including CXCR5 and CCR5, in breast cancer." (PMID 39001456, 2024). "In breast cancer, an anti-CXCL13 antibody suppressed tumor growth by inhibiting the TGF-β1, IL-1, TNF, cyclin D1, and CXCR5/Erk pathways and repressed tumor metastasis by inhibiting RANKL production." (PMID 34947813, 2021). "In breast cancer cells, the decrease in CXCL13 leads to the decreased expression of CXCR5, p-ERK/ERK, and cyclin D1 as well as the increased expression of cleaved Casp-9, which is an initiator caspase protease for apoptosis." (PMID 34947813, 2021). "A recent study showed that CXCL13 expression is increased in the sera of breast cancer patients with brain metastases, though the role and mechanism of action of the CXCL13/CXCR5 axis in cancer metastasis remain to be elucidated." (PMID 34947813, 2021). "In hypoxic environments, breast cancer cells express high levels of HIF-1, which promotes the expression of CXC chemokine receptor 3 (CXCR3) and CXC chemokine receptor 5 (CXCR5) on breast cancer cell lines." (PMID 24502410, 2014). "Examining the presence of CXCR5, which is the only known receptor for chemokine CXCL13, within breast cancer tissues, we detected only a comparably weak expression." (PMID 18781150, 2008). "We analysed six different breast cancer cell lines and found RNA and protein expressions of CXCL13 in all but one and CXCR5 expression in four of six cell lines." (PMID 18781150, 2008). "The expression of CXCL13 and CXCR5 was significantly higher in breast cancer tissue than in normal breast tissues." (PMID 39001456, 2024).
breast cancer (continued). "Multicolor immunophenotyping was used to determine the expression of PD‐1, TIM‐3, LAG3, CTLA‐4, CCR7, CD45RO, CD127, CD25, CXCR5, and ICOS molecules on CD3+CD4−CD56−CD8+ cytotoxic T cells freshly obtained from the lymph nodes and the peripheral blood samples of the breast cancer patients." (PMID 38069525, 2023). "Human breast cancer cells also express the CXCL-13 receptor, which induces the migration of CXCR-5-expressing B cells, and the coculture of CXCR-5-expressing B cells with cancer cells such as MCF-7 can induce the apoptosis of B cells and the appearance of a Breg population." (PMID 35746487, 2022). "Moreover, in a female BALB/c mouse model of breast cancer, an anti-CXCL13 antibody reduced tumor growth by impairing the CXCR5/Erk pathway and inducing tumor cell apoptosis." (PMID 34947813, 2021). "Analysis in breast cancer cell lines also revealed high levels of CXCL13 and expression of CXCR5." (PMID 31354634, 2019). "Our previous experiments on CXCR5 promoter regulation in an NFkB-dependent system based on breast cancer cell lines did not reveal any functional NFkB sites in the area of interest." (PMID 27909439, 2016). "Unfortunately, the lack of CXCR5 surface expression on breast cancer cell lines did not allow for consequent functional analyses of the role of CXCL13 in breast cancer in vitro." (PMID 18781150, 2008). "We show here for the first time that the ligand for CXCR5, CXCL13, is the most significantly overexpressed chemokine in breast cancer, supporting the idea of a role of CXCL13/CXCR5 interactions in promoting initiation and/or progression of this tumour type and, possibly, other human cancers." (PMID 18781150, 2008). "In addition, in a previous study, the expression profiles of CXCL12/CXCR4/CXCR7 and CXCL13/CXCR5 in the positive and negative LNs of breast cancer patients were found." (PMID 40584290, 2025). "Similarly, CXCL13/CXCR5 signaling can upregulate MMP-9 through the RANKL-Src axis, which other studies showed could facilitate lymph node metastasis in breast cancer." (PMID 40295829, 2025). "Although these findings, at first glance, do not support the concept of CXCR5 as the main target for CXCL13 overexpression in breast cancer, we believe that they do not reflect the potential role this chemokine receptor might play in vivo." (PMID 18781150, 2008). "Importantly, a concentration gradient- and time-dependent downregulation would also explain our observation of a strong correlation between CXCL13 expression and the presence of its receptor within breast cancer tissues despite the lack of CXCR5 overexpression in the same tissues." (PMID 18781150, 2008). "As expected, parental 4T1 and 4T1-CXCL13 cells showed no obvious CXCR5 expression both in vitro and in vivo, which can probably explain the previously contradictory findings of CXCL13 in breast cancer." (PMID 35693216, 2021).